GDF15 (growth differentiation factor 15)
Diseases named in the same sentence as GDF15 in open-access papers (continued):
Sharing a sentence is not in itself a finding about the gene and the disease.
heart failure (continued). "Studies have shown up‐regulation of GDF‐15 in cardiovascular diseases (cardiomyopathies, heart failure, atrial fibrillation, and stroke) and with type 2 diabetes, where higher levels associated with fasting glucose, insulin resistance index, and glycated hemoglobin." (PMID 32762010, 2020). "However, the expression and secretion of GDF15 can be strongly induced in the case of cardiovascular injury, such as pressure overload, myocardial infarction, heart failure, and atherosclerosis." (PMID 32222153, 2020). "Similarly, in a pressure overload model of heart failure, myocardial Gdf15 transcripts are elevated >5-fold after 4 weeks, but plasma levels were not different to control." (PMID 32310257, 2020). "GDF-15 is also suggested to be involved in the evolution of heart disease and to correspond with acute ischemia, ischemia-reperfusion injury, cardiac hypertrophy, and heart failure." (PMID 31772623, 2019). "GDF15, a stress-responsive transforming growth factor-beta-related cytokine, have been reported as a biomarker in cardiovascular disease as well as a strong prognosticator of heart failure." (PMID 29397400, 2018). "Growth differentiation factor 15 (GDF15) is currently being evaluated as a biomarker of cardiovascular stress and diseases that are linked to the incidence, progression, and prognosis of heart failure." (PMID 26909594, 2016). "In addition, GDF-15 is also related to cardiovascular diseases, such as heart failure, cardiac hypertrophy, and coronary heart disease (CHD)." (PMID 27154403, 2016). "Notably, GDF15 and GPNMB (patent publication number—WO2012072752 A1) have been proposed as diagnostic biomarkers of heart failure and were also up-regulated in our model system." (PMID 26537877, 2016). "GDF-15 is also correlated with NT-proBNP, reduced plaque burden, left ventricular mass, concentric left ventricular hypertrophy, coronary artery disease, and heart failure." (PMID 26273671, 2015). "In summary, GDF-15 is a very promising diagnostic marker for mild to moderate heart failure with normal ejection fraction or the absence of coronary artery diseases." (PMID 26273671, 2015). "There is a controversy regarding the production sites of GDF-15 during heart failure conditions." (PMID 26273671, 2015). "Indeed, in hypertensive patients, GDF15 was positively associated with the thickness of posterior wall of the left ventricle and left ventricular mass and treatment with recombinant GDF15 leads to a decrease in hypertrophy and reduced ventricular dilation in heart failure mice." (PMID 41303556, 2025). "Regarding cardiac hypertrophy, GDF15 levels correlate with increased left ventricular wall thickness in hypertensive patients, but studies in mice suggest that GDF15 may prevent or reduce hypertrophy and heart failure." (PMID 40837873, 2025). "A complex model, including both N-terminal pro-brain natriuretic peptide (NT-proBNP) and GDF-15, may play a supplemental role to support the treatment based only on BNP and better predict all-cause mortality and heart failure rehospitalization during a one-year follow-up." (PMID 40385809, 2025). "GDF‐15, also referred to as the macrophage inhibitory cytokine 1, is a stress‐inducible cytokine and atypical member of the transforming growth factor‐β (TGF‐β) superfamily, which has emerged as a marker of all‐cause mortality in heart failure and cancer, among others." (PMID 41287825, 2025). "Taken together, elevated GDF-15 levels after MI may exert a protective function by reducing proinflammatory immune cell recruitment and, thereby, MI complications, such as cardiac remodeling and heart failure." (PMID 39000420, 2024). "The strong correlations of GDF15 in plasma and parameters of heart function in the mice lacking Yme1l and exhibiting dilated cardiomyopathy, suggest that GDF15 may have broad applicability in driving the severity of heart failure in cardiac cachexia." (PMID 39312445, 2024).
heart failure (continued). "As a sensitive marker of cardiopulmonary stress, GDF15 has no known specific diagnostic function in different diseases such as heart failure, pneumonia, COPD, nephropathy, and septicaemia, although its expression is markedly increased in patients with acute exacerbations of COPD." (PMID 37093513, 2024). "Finally, we also provide evidence that suggests GDF15 may contribute to cachexia in patients with heart failure." (PMID 39312445, 2024). "Also, this high expression has been reported after MI leading to the suggestion that GDF-15 may be a biomarker for heart failure." (PMID 37974205, 2023). "Additionally, GDF15 is also crucial in various pathophysiological changes in the cardiovascular system, such as heart failure, hypertension, vascular contraction and atrial fibrillation, which have been described and reviewed in detail in multiple prior studies." (PMID 36992609, 2023). "Population studies have also demonstrated positive correlations between increased GDF-15 levels and the increased risk of cardiovascular events, emphasizing its potential importance as an independent predictor of mortality in patients with CAD and heart failure." (PMID 37888100, 2023). "As many anticancer drugs are cardiotoxic and GDF15 is a well-known biomarker for heart failure, we employed a human induced pluripotent stem cell-derived cardiomyocytes (hiPSC-CMs) model to investigate the effect of drug-induced cardiotoxicity on GDF15 expression in host tissues." (PMID 37495707, 2023). "Interestingly, elevated circulating GDF15 was reported in patients with pulmonary arterial hypertension and heart failure, but it is unclear whether GDF15 contributes to cachexia in these disease conditions." (PMID 35406637, 2022). "However, pirfenidone did not cause a decrease in expression of heart failure related protein GDF-15, nor did it significantly influence the expression of plasminogen related proteins PAI, uPA and U-PAR which were all upregulated by TGF-β1 stimulation." (PMID 35360018, 2022). "GDF-15 blood levels are extensively being explored as a cardiovascular disease marker indicative of metabolic health, and are reported to be increased in ischemia, heart failure, and hypertrophic and dilated cardiomyopathy, and in patients with type 2 diabetes at greater risk of heart failure." (PMID 36361969, 2022). "Similarly, GDF-15, a pleiotropic cytokine is known as a biomarker of heart failure." (PMID 35059851, 2022). "Therefore, we presumed that GDF-15 may have a possible, indirect mechanism with volume overload and heart failure in patients on hemodialysis." (PMID 35204349, 2022). "Plasma growth differentiation factor-15 (GDF-15) biomarker levels increase in response to inflammation and tissue injury, and increased levels of GDF-15 are associated with increased risk of mortality in patients with heart failure with reduced ejection fraction (HFrEF)." (PMID 35219331, 2022). "From the same study, it was recently reported that 9 proteins (GDF-15, TIM-1, TRAIL-R2, SPON1, MMP-12, follistatin [FS], soluble urokinase-type plasminogen activator surface receptor [sU-PAR], OPG, and sST2) were associated with the development of heart failure." (PMID 33439866, 2021). "However, no significant causal association was observed for circulating GDF-15 levels with the incidence of any ischemic stroke, large-artery atherosclerotic stroke, small vessel stroke, heart failure and nonischemic cardiomyopathy." (PMID 33115406, 2020). "However, GDF-15 could be markedly increased in the case of cardiovascular injury, such as pressure overload, myocardial infarction, heart failure, and atherosclerosis." (PMID 32746821, 2020). "Modulation of the GDF15-GFRAL axis may also be beneficial for the treatment of other anorexia/cachexia syndromes, for example, end-stage renal disease, heart failure, and COPD, which are all associated with anorexia/cachexia syndromes that confer an adverse prognosis." (PMID 32310257, 2020).
heart failure (continued). "GDF15 could be an integrative biomarker of heart failure in patient with AMI." (PMID 32746821, 2020). "GDF-15 can be used as a prognostic marker in patients with cardiovascular disorders in combination with conventional prognostic factors such as NT-proBNP and hs-TnT, as it is induced in hypertrophic and dilated cardiomyopathy after volume overload, ischemia and heart failure." (PMID 32899694, 2020). "Elevations in GDF15 are not limited to these physiological states and in the 20 years since its discovery, increases in the peptide have been reported in a variety of pathological conditions including aging, cardiac failure, chronic kidney disease, mitochondrial disease and malignancy." (PMID 31801546, 2019). "However, more studies need to be done to distinguish different kinds of heart failure using GDF-15." (PMID 26273671, 2015). "Proteins that were selected by Lasso regression for each outcome that commonly included GDF15 and IL6, significantly improved the prediction of mortality, mobility limitation, and heart failure compared with age, sex, and race alone." (PMID 39695064, 2025). "In clinical practice, various biomarkers have been utilized for the diagnosis and prognosis assessment of heart failure, such as BNP, NT-proBNP, cTn, galectin-3, sST2, and growth differentiation factor-15." (PMID 40406620, 2025). "Promising novel biomarkers that showed good performance in detecting diastolic dysfunction or heart failure in diabetic patients include galectin-3, ST2, FGF-21, IGFBP-7, GDF-15, and TGF-β." (PMID 39335666, 2024). "We found elevated levels of the circulating biomarkers suPAR, GDF-15, VCAM-1, and H-FABP in patients with heart failure." (PMID 39598008, 2024). "There are some promising novel biomarkers, such as galectin-3, ST2, FGF-21, IGFBP-7, GDF-15, and TGF-β, that provide good specificity in diagnosing diastolic dysfunction or overt heart failure in diabetic patients." (PMID 39335666, 2024). "Other emerging biomarkers that may predict cardiac involvement and the risk of heart failure (HF), such as interleukin-33R (IL-33R), which is also known as suppression of tumorigenicity 2 protein/interleukin-33R (ST2/IL-33R) and growth differentiation factor 15 (GDF-15), have been recently studied." (PMID 36612202, 2022). "Causal relationship of circulating GDF-15 levels with the increased risk of cardioembolic stroke, atrial fibrillation, coronary artery disease and myocardial infarction, but not any IS, large-artery atherosclerotic stroke, small vessel stroke, heart failure, and nonischemic cardiomyopathy." (PMID 34456968, 2021). "Biomarkers analyzed in pre-surgery plasma were categorized based on function: inflammation-related (NLR, GDF15, Galectin3, ST2, TNFR2), heart failure (HF)/remodeling related (NT-proBNP) and metabolism-related (glycemia, lipid profile)." (PMID 32671100, 2020). "Biomarker screening was classified by inflammation(NLR, GDF15, Galectin3, ST2, TNFR2), heart failure(HF)/remodeling(NT-proBNP) and metabolism(glycemia, lipid profile)." (PMID 32671100, 2020). "Moreover, serum GDF-15, a stress-responsive cytokine of the TGF-β superfamily, produced in pathophysiological situations associated with inflammation and tissue injury (e.g., heart failure), was significantly increased in elderly patients with both MDs and CVDs compared with YH and EH controls." (PMID 33080827, 2020). "Additional biomarkers tested in pre-surgery plasma were related to inflammation (NLR, GDF15, Galectin3, ST2, TNFR2), heart failure (HF)/remodeling (NT-proBNP) and metabolism (glycemia, lipid profile)." (PMID 32671100, 2020). "Growth differentiation factor-15 (GDF-15), also known as macrophage inhibitory cytokine-1 (MIC-1), along with NT-proBNP, cTn-hs, age and heart failure diagnosis, have been reported to predict death in AF." (PMID 31280356, 2020).
heart failure (continued). "Background: we aimed at investigating the influence of weightlessness and hypergravity by means of parabolic flight on the levels of the heart failure biomarkers H-FABP, sST2, IL-33, GDF-15, suPAR and Fetuin-A." (PMID 32423045, 2020). "The prognostic value of GDF-15 has been reported for various cardiovascular diseases, such as ACS, atrial fibrillation, and heart failure." (PMID 32746821, 2020). "Growth differentiation factor-15 (GDF-15) involves various pathophysiological conditions including renal dysfunction, heart failure and cachexia." (PMID 31581569, 2019). "The aim of this study was to investigate the predictive value of single and repeated measurements of GDF-15 compared to Cystatin C and CRP for incidence of heart failure (HF) and death due to coronary heart disease (CHD) in the general population." (PMID 29771963, 2018). "In some disease states such as chronic renal and cardiac failure and advanced cancer, MIC-1/GDF15 expression is dramatically increased by up to 10–100 fold." (PMID 28081177, 2017). "Increased concentrations of growth differentiation factor 15 (GDF-15) and high-sensitivity troponin T (hsTnT) were found in patients with both HFpEF and heart failure with reduced ejection fraction (HFrEF) as compared to community-based controls." (PMID 25802475, 2015). "Addition of GDF15, PARC, and MMP7 increased the C-statistic for heart failure from 0.59 to 0.70." (PMID 39695064, 2025). "On the other hand, iEATv and novel biomarkers (GDF15, Galectin-3, and sST2) are validated surrogates for inflammation and remodeling, but they do not replace hard endpoints, such as incident heart failure or hospitalization." (PMID 40649060, 2025). "It included proteins like NT-proBNP (NPPB), growth differentiation factor 15 (GDF15), and fibroblast growth factor 23 (FGF23), markers that are known to be tightly related to heart failure and further systemic diseases, but also inflammatory proteins (CXCL8, CSF1)." (PMID 38999939, 2024). "These included proteins involved in atherosclerosis/inflammation (e.g. GDF-15, lipopolysaccharide binding protein, and CD14), extracellular matrix [matrix metalloproteinase-7 (MMP7)], heart failure [N-terminal pro-B-type natriuretic peptide (NT-proBNP)], and renal insufficiency cystatin C (CST3)." (PMID 39660078, 2024). "Therefore, we evaluated the circulating biomarkers GDF-15, H-FABP, suPAR, and VCAM-1 in a single center cohort of advanced heart failure patients clinically presenting in the chronic and acute forms, thus aiming to show their sensitivity to HF decompensation." (PMID 39598008, 2024). "The other mouse models of heart failure do not appear to be severe enough in terms of cellular stress and mitochondrial dysfunction to induce high GDF15 production and lead to cardiac cachexia." (PMID 39312445, 2024). "The median level of GDF-15 among our subjects was higher than observed in a general population of the same age but lower than in a population with Acute coronary syndrome (ACS), heart failure, and also among subjects with severe lower limb ischemia." (PMID 39780955, 2024). "Increased GDF-15 levels are shown to be related to CVD, such as atherosclerosis and heart failure." (PMID 37888100, 2023). "Although the exact correlation between GDF-15 and OH/ECW has not been fully evaluated, serum GDF-15 was reported to be elevated in patients with heart failure." (PMID 35204349, 2022). "Beside the classic marker that is CRP (which is an independent prognostic factor for adverse events in patients with heart failure) or NT-proBNP, an increased concentration of TNF- α, ST2, IL-1, IL-6, IL-8, Galectin-3 (Gal-3), and growth differentiation factor 15 (GDF15) was also observed." (PMID 35269577, 2022). "Concerning the heart, GDF15 is not normally expressed in the adult myocardium, although it is significantly induced after “injury” or in heart failure." (PMID 34445593, 2021).
heart failure (continued). "Nonetheless, some authors found GDF15 levels to be associated with impairment in exercise capacity in patients with the heart failure syndrome whereas others do not consider GDF15 as a reliable biomarker of exercise capacity in heart failure patients." (PMID 33329017, 2020). "Inconsistently, BIOSTAT-CHF trial has reported that GDF-15 levels were not influenced by the presence of atrial fibrillation (AF) in patients with heart failure (HF)." (PMID 33115406, 2020). "Clinical trials reported that GDF-15 is a reliable biomarker of CVD, and heart failure, and it has independent prognostic value in patients with coronary artery bypass grafting (CABG), acute coronary syndromes (ACS), and heart failure (HF)." (PMID 31581569, 2019). "In recent years, circulating GDF-15 has been identified as a biomarker with prognostic value in cardiopulmonary diseases like heart failure, ST- and non-ST-elevation myocardial infarction, and pulmonary embolism." (PMID 29180833, 2017). "As expected, the serum concentrations of NT-proBNP and GDF15 (not shown), two biomarkers of heart failure, were elevated above the range generally observed in healthy individuals." (PMID 24260393, 2013). "Additionally, we provide new insight into the perioperative trajectories of two biomarkers of heart failure and cardiac remodelling (NT-proBNP and GDF-15) in patients with or without preoperative inflammation." (PMID 40491666, 2025). "GDF-15 and BNP levels predict increased mortality risk in heart failure (HF) cases, irrespective of whether the ejection fraction (EF) is preserved or reduced." (PMID 39781722, 2025). "GDF-15 and BNP levels are predictive indicators for evaluating the increased mortality risk in heart failure cases, irrespective of whether the ejection fraction is preserved or reduced." (PMID 39781722, 2025). "Although a clear biomarker of heart failure, it is not known whether GDF15 plays a contributory or protective role in this context." (PMID 39312445, 2024). "In thisregard, GDF-15 did not reflect overlapping disease pathways that might contributeto the development of heart failure after ACS, because prognostic information wasindependent of clinical predictors and markers like hs-CRP and BNP." (PMID 39077481, 2023). "GDF15 is similarly elevated in stable heart failure with and without reduced ejection fraction." (PMID 32310257, 2020). "GDF-15 and NT-proBNP predicted CLT in unadjusted model, after adjustment for age, sex, BMI and fibrinogen as well as after additional adjustment for coronary artery disease, heart failure/left ventricular dysfunction, GFR, antiplasmin, PAI-1, TAFI, CRP, cTnI-hs." (PMID 31280356, 2020). "Recently, growth differentiation factor-15 (GDF-15), a member of the transforming growth factor-beta superfamily, has been identified as a novel and promising candidate across a spectrum of CVD ranging from acute ischemic events through chronic atherosclerotic disease to manifest heart failure." (PMID 32993054, 2020). "GDF-15 is not expressed in heart under normal physiological conditions but increases rapidly in response to cardiovascular injury, such as pressure overload, heart failure, ischemia/reperfusion, and atherosclerosis." (PMID 26273671, 2015). "Indeed, in a randomized controlled clinical trial of sacubitril/valsartan, which prevents adverse cardiac remodeling, reduces heart failure morbidity and mortality, and reduces indices of cardiac stress, GDF15 was not different in placebo and experimental arms." (PMID 32310257, 2020). "In our study, we evaluated the serum levels of sST-2, GDF-15, suPAR and H-FABP in 92 patients with the suspicion of TTS (51 TTS and 41 ACS patients) and 40 gender matched controls (no coronary artery disease or signs of heart failure) at baseline." (PMID 34727211, 2022).